MOG (myelin oligodendrocyte glycoprotein)
Diseases named in the same sentence as MOG in open-access papers (continued):
Sharing a sentence is not in itself a finding about the gene and the disease.
myelitis (continued). "Seven patients (7/28, 25.0%) in the AQP4-ON group had a clinical history of myelitis, with myelitis occurring less frequently in the MOG-ON (1/26, 3.8%) and IDON (0/29, 0.0%) patients (P = 0.002)." (PMID 35615385, 2022). "In a group of 10 immunocompetent patients with VZV infection–related myelitis, MOG-IgG was present in one patient." (PMID 34737756, 2021). "In synopsis with the MOG-IgG associated cases, eleven patients out of twelve presented with LETM (the one remaining case was MRI-negative myelitis), LETM seems to be a typical clinical presentation of these rare associations." (PMID 34737756, 2021). "The MOG-IgG- group had a clinical diagnosis as follows: 25.9% had ON, 27.6% had myelitis, 3.5% were clinically diagnosed with seronegative NMOSD, 5.2% were diagnosed with AQP4-NMOSD." (PMID 34025652, 2021). "Clinical manifestation can be a mixture of typically associated syndromes, e.g. ataxia associated with anti-ITPR1 antibodies, encephalomyelitis with anti-GFAPα antibodies and longitudinal extensive myelitis with anti-MOG antibodies." (PMID 34635185, 2021). "About disease presentation, in the MOG-IgG+ group the majority of patients (65.9%) presented with ON, 14.7% had myelitis, 2.4% had both ON and myelitis, 7.3% were clinically diagnosed with seronegative NMOSD, 7.3% had ADEM, and 2.4% had epileptic seizures." (PMID 34025652, 2021). "Elevated AI’s were observed against 5 bacterial lysates in subject DD-82, a young woman with anti-MOG myelitis." (PMID 34100959, 2021). "We confirm rarer presenting features or “red flags” suggesting MOG-antibody positivity in patients, such as seizures with cortical lesions and conus medullaris involvement in patients with myelitis." (PMID 33510701, 2020). "ADEM-like disease is the predominant clinical presentation in young children, whereas in older children with MOG-IgG there is a shift toward ON, myelitis, and/or brainstem symptoms." (PMID 32883358, 2020). "Magnetic resonance imaging from the MOG autoantibody–positive patient’s first clinical attack showed long extensive myelitis and a pontine lesion." (PMID 30824481, 2019). "Plasma exchange (regime varying from three to five cycles) is more commonly used as a second-line treatment following steroid resistance and can result in around 40% of cases of MOG antibody ON and/or myelitis having a complete or almost complete recovery." (PMID 30569382, 2019). "Serum laboratory testing for anti-AQP4 and MOG antibodies through cell-based assays should be considered in any child with myelitis, as a positive result would be clinically significant in relation to ongoing surveillance and management." (PMID 31109018, 2019). "Intravenous methylprednisolone (IVMP) for the treatment of MOG antibody positive ON and/or myelitis (dose ranging from 1 to 2 g once a day for 3–5 days) has been reported to be effective in some cases, with partial or no recovery in 50%." (PMID 30569382, 2019). "In this case report a MOG-IgG syndrome patient with recurrent ON, clinical symptoms consistent with myelitis with a sensory level, and recurrent meningoencephalitis was described." (PMID 31072329, 2019). "A higher prevalence of myelitis with clinical attacks and chronic spinal cord lesions was detected for AQP4-IgG-seropositive NMOSD patients in comparison to MOG-IgG-associated diseases." (PMID 31345223, 2019). "Of note, we also observed MOG-Ab in a patient with definite diagnosis of MS characterised by ON at onset, recurrent myelitis, CSF restricted OB and typical brain and spinal cord MRI features." (PMID 29063242, 2017). "Based on these preliminary yet promising results, further retrospective studies seem warranted to assess the efficacy of MTX in MOG-IgG-positive ON and/or myelitis." (PMID 27793206, 2016). "Overall, 40 (89 %) of 45 follow-up samples from MOG-IgG-positive patients with ON and/or myelitis were positive after a median interval between first and last sampling of 16.5 months (range 0–123)." (PMID 27788675, 2016).
myelitis (continued). "Systematic studies on the potential prognostic, diagnostic, and therapeutic implications of pathological EP and MRI findings suggesting dissemination in space in patients with MOG-IgG-positive isolated ON or isolated myelitis are warranted." (PMID 27793206, 2016). "Data on somatosensory evoked potentials (SSEP) were available from 39 MOG-IgG-positive patients, including 24 with a history of clinically manifest myelitis." (PMID 27793206, 2016). "If only patients with MOG-IgG-positive isolated myelitis are considered, 4/6 had recurrent myelitis and two had monophasic myelitis." (PMID 27788675, 2016). "Seven of 46 (15.2 %) MOG-IgG-positive patients with a history of myelitis and/or ON and 7/26 (26.9 %) of those with brain lesions met Barkhof’s MRI criteria for MS at least once." (PMID 27793206, 2016). "This needs to be kept in mind when deciding on long-term treatment, and attention should be paid to signs or symptoms of additional brainstem involvement in patients with MOG-IgG-positive ON and/or myelitis." (PMID 27802825, 2016). "MOG-IgG-positive ON and myelitis are increasingly recognized as important differential diagnoses of AQP4-IgG-positive NMOSD." (PMID 27793206, 2016). "In our cohort, eight MOG-IgG-positive patients with ON and/or myelitis were treated with MTX, and exact data on attack dates were available from six." (PMID 27793206, 2016). "MRZR was tested in 11 MOG-IgG-positive patients (2 x ON + myelitis; 1 x ON + myelitis + brainstem encephalitis; 1 x myelitis + brainstem encephalitis; 3 x LETM; 5 x ON) and was negative in all of them." (PMID 27793206, 2016). "Given the high frequency of flare-ups observed in our cohort, close clinical monitoring after acute attack therapy for MOG-IgG-positive ON and/or myelitis is recommended." (PMID 27793206, 2016). "Studies systematically investigating the efficiency of long-term immunosuppression and/or immunomodulation in MOG-IgG-positive ON and myelitis are therefore strongly warranted." (PMID 27793206, 2016). "The efficacy of PEX in this and other cases of MOG-IgG-positive ON and/or myelitis has potentially important pathophysiological implications, since it suggests a direct pathogenic role of the antibody." (PMID 27793206, 2016). "This suggests that MOG-IgG testing should be considered both in patients with monophasic and in patients with recurrent myelitis." (PMID 27788675, 2016). "In summary, our study demonstrates that brainstem involvement is common in patients with MOG-IgG-related ON and/or myelitis." (PMID 27802825, 2016). "Given the relapsing and often severe disease course of MOG-IgG-positive ON and myelitis, the use of long-term immunosuppressive treatments in this condition should be considered." (PMID 27793206, 2016). "It is of clinical relevance that 15/28 (53.6 %) of the MOG-IgG-positive patients with a history of myelitis identified in this study had recurrent attacks of myelitis." (PMID 27788675, 2016). "Outcome data were available for 134 ON attacks in 39 MOG-IgG-positive patients and for 46 myelitis attacks in 23 MOG-IgG-positive patients." (PMID 27793206, 2016). "In part 2, we systematically evaluate the clinical and paraclinical features present in MOG-IgG-positive ON and/or myelitis as well as treatment responses and long-term outcome." (PMID 27788675, 2016). "Among 50 patients with MOG-IgG-positive ON and/or myelitis, 15 (30 %) with a history of brainstem encephalitis were identified." (PMID 27802825, 2016). "The predominantly relapsing and often severe disease course and the short median time to second attack support the use of prophylactic long-term treatments in patients with MOG-IgG-positive ON and/or myelitis." (PMID 27793206, 2016). "Detailed clinical and paraclinical data were available for all 50 MOG-IgG-positive patients with ON and/or myelitis identified in this study and are comprehensively analyzed in parts 2, 3 and 4 of this series." (PMID 27788675, 2016).
myelitis (continued). "Brainstem involvement is present in around one third of MOG-IgG-positive patients with ON and/or myelitis." (PMID 27802825, 2016). "Although MRI-negative myelitis can be observed in myelin oligodendrocyte glycoprotein antibody-associated disease (MOGAD), lupus myelitis, and glial fibrillary acidic protein (GFAP) astrocytopathy, post-COVID-19 myelitis lacks specific biomarkers, complicating both diagnosis and treatment." (PMID 41451231, 2025). "We hypothesized that more sensitive AQP4-IgG assays and availability of MOG-IgG testing would identify AQP4-IgG seropositive NMOSD and MOGAD as prevalent causes of myelitis (particularly LEM) in patients with rheumatologic diseases." (PMID 39442039, 2025). "Multivariate analysis showed that longitudinally extensive myelitis and AQP4-IgG are independent risk factors for the development of spinal movement disorders, while MOG-IgG and African American race were associated with a lower risk of developing these movement disorders." (PMID 38977461, 2024). "We then performed a review of current literatures, using “myelin oligodendrocyte glycoprotein” or “MOG” as the search terms, to identify research studies performed on myelin oligodendrocyte antibody-positive myelitis focusing on the description of the “H-sign” and enhancement pattern." (PMID 39318613, 2024). "Based on these numbers, testing MOG antibodies in patients with low probability of MOGAD, e.g. including all MS-caused ON and myelitis cases, would result in a significant number of false-positive MOG antibody results in patients with low positive MOG serotiters." (PMID 37744325, 2023). "Myelitis (11/17 [65%]) was the most frequent disease manifestation, followed by brainstem syndrome (7/16 [44%] vs 14/75 [19%], respectively; P = .048), which occurred at a higher frequency than in patients with MOG-IgG." (PMID 37548987, 2023). "Studies have suggested that MOG-IgG titers are higher during relapses and may be highest in patients presenting with myelitis or ADEM." (PMID 35401423, 2022). "Myelitis presenting as rapid onset of paraparesis or quadriparesis may be associated with AQP4 antibodies (NMO spectrum disease); MOG antibodies (MOG antibody- associated disease); MS or ADEM." (PMID 33935958, 2021). "Spinal cord MRI can be initially normal in myelitis patients with MOG autoantibodies." (PMID 34305787, 2021). "Our case indicates that MOG IgG testing could be considered in the case of COVID-19 infection preceding ON or myelitis." (PMID 34106635, 2021). "Although ON and myelitis are the two most frequent forms of presentation of anti-MOG ab disease, coexistence of brain, brainstem, or cerebellar involvement is frequent, and may even be extensive." (PMID 32455910, 2020). "Consistent with previous studies, ON, myelitis, and/or brainstem symptoms were the predominant clinical features in most adult MOG-encephalomyelitis patients, whilst in children and younger adults there was a shift toward ADEM imitation, with encephalopathy as a clinical characteristic." (PMID 31080435, 2019). "A small proportion (7%) of MOG-IgG-seropositive patients were reported to present with short myelitis occurring after an initial episode of LETM, isolated at disease onset, or following previous episodes of ON (which could initially suggest MS)." (PMID 29670575, 2018). "Whereas MOG Abs are only transiently observed in monophasic diseases such as ADEM and their decline is associated with a favorable outcome, they are persistent in multiphasic ADEM, NMOSD, recurrent ON, or myelitis." (PMID 28533781, 2017). "MTX was identified as a potentially effective treatment in MOG-IgG-positive ON and/or myelitis." (PMID 27793206, 2016). "In group I (samples sent in for routine assessment of MOG-IgG), MOG-IgG was detected in 95/386 (24.6 %) samples from 50/300 (16.7 %) patients; if only patients with a diagnosis of ON and/or myelitis are considered, MOG-IgG was present in 95/281 (33.8 %) samples from 50/202 (24.8 %) patients." (PMID 27788675, 2016).
myelitis (continued). "Thirdly, we cannot fully exclude a potential referral bias, since MOG-IgG testing may have been ordered particularly in patients presenting with ON and/or myelitis based on the previous literature." (PMID 27802825, 2016). "As MOG-IgG-positive brainstem encephalitis may take a serious or even fatal course, particular attention should be paid to signs or symptoms of additional brainstem involvement in patients presenting with MOG-IgG-positive ON and/or myelitis." (PMID 27802825, 2016). "Our case showed that influenza infection may trigger anti-MOG-IgG positive myelitis; following treatment, the titer of anti-MOG antibody decreased together with clinical symptoms." (PMID 25434485, 2014). "Interestingly, MOG-IgG-seropositive patients showed a swelling of the upper cervical cord area during other non-myelitis attacks, also pointing towards a systemic inflammatory affection in MOG-IgG-associated diseases as potentially shown here in the pRNFL during different attacks." (PMID 31345223, 2019). "While some patients with MOG-IgG-positive ON and/or myelitis meet the 2015 international diagnostic criteria for NMOSD, others do not; this is problematic from a nosological point of view, assuming that the same immunopathogenesis underlies all MOG-IgG positive cases." (PMID 27793206, 2016). "Moreover, MS was initially suspected in more than a third of all patients, and every fourth patient with MOG-IgG-positive ON and/or myelitis presenting with brain and/or brainstem lesions met Barkhof’s criteria for MS, demonstrating a substantial phenotypic overlap between these two conditions." (PMID 27793206, 2016). "Further research is needed to characterize myelitis etiology in patients who are seronegative for both AQP4-IgG and MOG-IgG." (PMID 39442039, 2025). "ON was the most represented first clinical event in our entire cohort (more often bilateral in anti-MOG than anti-AQP4 in larger cohorts than ours), followed by myelitis and the simultaneous attack of both regions." (PMID 34097296, 2022). "There was a tendency(p<0.1) for a higher frequency of myelitis in patientswith increased CSF IL-6 levels in both subgroups and for increased serum GRO-αlevels in MOG-Ab positive children." (PMID 31205739, 2019). "Eight MOG-IgG-positive patients had a previous diagnosis of AQP4-IgG-negative NMOSD with ON and myelitis, and eight of (mainly recurrent) ON." (PMID 27802824, 2016). "A negative MRI in a patient presenting acutely with clinical features of myelitis should not deter from testing for MOG antibody." (PMID 37483456, 2023). "After severe and/or recurrent myelitis attacks, MRI may also show (longitudinally extensive) spinal cord atrophy in NMOSD (but also in MOG-EM and in long-standing MS)." (PMID 37022481, 2023). "One of the limitations presented by the study was the low percentage of patients tested for anti-MOG and a possible association of patients with ADEM-like phenotype and/or concomitant neuritis and myelitis not being associated with a worse prognosis." (PMID 35296261, 2022). "In our study, symptoms of myelitis were more predominant in patients with AQP4-abs than in those with MOG-abs either at onset or relapse, but LETM did not help distinguish between the two groups, similar to other reports." (PMID 33841310, 2021). "In a subsequent retrospective study of 59 patients with VZV infection and neurological involvement; however, we did not found MOG-IgG in any patient (including 15 with VZV encephalitis/myelitis)." (PMID 34737756, 2021). "A study found that patients with MOG antibody ON and/or myelitis treated with azathioprine, but not adjunctively with oral steroids, experienced relapses more commonly than patients who underwent combination therapy." (PMID 30569382, 2019). "ON was more frequently observed in MOG-Ab positive subjects compared with MOG-Ab negative cases, with a statistically significant difference, while the occurrence of myelitis was more frequent in MOG-Ab negative cases." (PMID 29063242, 2017).
myelitis (continued). "Of these, only 2 samples (from a patient with a history of ON and myelitis) were positive for MOG-IgM and none for MOG-IgA." (PMID 27788675, 2016). "By contrast, necrotic lesions leading to spinal cord cavitation, as sometimes noted in AQP4-IgG-positive myelitis, were not reported in any of our MOG-IgG-positive patients." (PMID 27793206, 2016). "MOG-IgG is present in a substantial subset of patients with ON and/or myelitis, but not in classical MS." (PMID 27788675, 2016). "Although in our cohort most patients with MOG-IgG-positive myelitis had LETM, non-longitudinally extensive lesions were found on a number of MRI examinations and thus do not preclude the diagnosis." (PMID 27793206, 2016). "The relative frequencies of MOG-IgG in group I patients with a history of ON and myelitis, myelitis but not ON, and ON but not myelitis, respectively, were 22/54 (40.7 %), 22/103 (21.4 %), and 6/45 (13.3 %)." (PMID 27788675, 2016). "Isolated attacks of brainstem encephalitis, i.e., attacks that were not accompanied by clinical symptoms of ON or myelitis, were very rare in the total cohort of 50 MOG-IgG-positive patients, accounting for only 5/276 (1.8 %) documented attacks." (PMID 27802825, 2016). "Thirty-four follow-up samples were obtained from patients with ON and/or myelitis from group I who were negative at first testing; all of them were negative for MOG-IgG as well." (PMID 27788675, 2016). "The presence or absence of ‘short’ lesions in patients with AQP4-IgG- or MOG-IgG-positive myelitis is thought to depend, among other factors, on timing issues." (PMID 27793206, 2016). "While these preliminary data are not supportive of the use of NAT in MOG-IgG-positive ON or myelitis, systematic studies are certainly needed before definite conclusions can be drawn." (PMID 27793206, 2016). "On the understanding that MOG-IgG-positive ON and/or myelitis are not considered “alternative diagnoses”, i.e., based solely on clinicoradiologic findings, 9/15 (60 %) met the revised 2015 consensus criteria for NMOSD." (PMID 27802825, 2016). "While myelitis is typically longitudinally extensive—extending over three or more complete vertebral segments—in both AQP4-IgG-positive and AQP4-IgG-negative NMOSD (and MOG-EM/MOGAD) long lesions are extremely rare in MS and, if present, usually result from the coalescence of adjacent lesions." (PMID 37022481, 2023). "Myelitis in NMOSD may also mimic spinal cancer or lymphoma and vice versa; whenever possible, AQP4-IgG (and MOG-IgG) should be tested and NMOSD excluded before a decision is made to perform spinal cord biopsy—a procedure that can leave patients severely disabled—for suspected spinal neoplasia." (PMID 37022481, 2023). "All seven (100%) patients in the ADEM without MOG-abs group also had symptoms of myelitis." (PMID 33329345, 2020). "Taking only MOG-IgG-positive patients with a history of both ON and myelitis into account, 10/20 or 50 % with available data fulfilled those criteria, compared with 7/31 or 23 % with a history of ON but not myelitis or of myelitis but not ON at last follow-up." (PMID 27793206, 2016). "Our series, which includes some of the youngest as well as the oldest Caucasian MOG-IgG-positive cases, demonstrates that MOG-IgG positivity should be considered in patients presenting with ON or myelitis of unknown origin irrespective of age." (PMID 27793206, 2016). "All MOG-IgG-positive patients in group I had a history of ON and/or myelitis; 22/50 (44 %) had a history of both ON and myelitis; 22/50 (44 %) had a history of ON but not of myelitis (recurrent in 13); and 6/50 (12 %) had a history of longitudinally extensive myelitis (LETM) but not of ON." (PMID 27788675, 2016). "However, it remains unclear whether MOG-IgG-positive ON or myelitis should be considered an “alternative diagnosis” or not." (PMID 27793206, 2016).